SBF2-AS1 (SBF2 antisense RNA 1)
Gene: Long non-coding RNA gene on chromosome 11 (9,758,267 to 9,811,335, forward strand). Ensembl gene ENSG00000246273.
Gene Ontology:
Biological process: SRP-dependent cotranslational protein targeting to membrane, signal sequence recognition
Cellular component: signal recognition particle, endoplasmic reticulum targeting
Diseases named in the same sentence as SBF2-AS1 in open-access papers:
SBF2-AS1 is named in the same sentence as 2 diseases in open-access papers, as found by Europe PMC text mining. Sharing a sentence is not in itself a finding about the gene and the disease. The quoted sentences say what the papers report.
glioblastoma (1 paper, 2025). The most malignant astrocytic tumor (WHO grade IV). "High levels of SBF2 antisense RNA 1 (SBF2-AS1) were detected in exosomes secreted from glioblastomas (GBM) cells and were associated with poor response to temozolomide (TMZ)." (PMID 39925739, 2025).
glioma (1 paper, 2017). A benign or malignant brain and spinal cord tumor that arises from glial cells (astrocytes, oligodendrocytes, ependymal cells). "Furthermore, long non-coding RNA SBF2 antisense RNA 1 (SBF2-AS1) was upregulated in glioma samples and knockdown of SBF2-AS1 impaired GBM-induced angiogenesis." (PMID 28983240, 2017).